MC3R (melanocortin 3 receptor)
Diseases named in the same sentence as MC3R in open-access papers (continued):
Sharing a sentence is not in itself a finding about the gene and the disease.
osteoarthritis (1 paper, 2025). A noninflammatory degenerative joint disease occurring chiefly in older persons, characterized by degeneration of the articular cartilage, hypertrophy of bone at the margins and changes in the synovial membrane. "Activation of MC1R and MC3R via agonists can be used to counter inflammatory and degenerative changes in rheumatoid and osteoarthritis." (PMID 41002740, 2025).
periodontal disease (1 paper, 2018). "Furthermore, in line with data obtained from bone-marrow-derived osteoclasts, a physiologic control of osteoclast reactivity was observed exerted by MC3R by demonstrating that Mc3r-null mice develop periodontal disease with accelerated kinetics as they age." (PMID 29373492, 2018).
metabolic disease (4 papers, 2013 to 2026). A congenital disorder (due to inherited enzyme abnormality) or acquired (due to failure of a metabolically important organ) disorder resulting from an abnormal metabolic process. "Unlike the clear role of MC3R and MC4R on metabolism, evidenced by the fact that MC4R KO and to a lesser extent MC3R KO mice develop obvious metabolic disorders, its role in reproduction remains uncertain." (PMID 24101924, 2013). "Targeting neural MCRs (MC3R and MC4R) is emerging as a therapeutic approach for metabolic diseases and chronic inflammation." (PMID 36291616, 2022).
MC3R also shares sentences with these, for which no sentence is quoted: tumor (12 papers); cancer (8); breast carcinoma (4); type 2 diabetes (3); cardiovascular disease (2); COVID-19 (2); depression (2); eating disorder (2); infection (2); joint disease (2); melanoma (2); pancreatic cancer (2); amyloidosis (1); asthma (1); autism (1); autoimmune disorders (1); Bardet-Biedl syndrome (1); brain tumors (1); breast tumors (1); candidiasis (1); cerebral artery (1); colon cancer (1); Delayed puberty (1); familial glucocorticoid deficiency (1); glioma (1); Hepatic steatosis (1); Hypercholesterolemia (1); hyperlipidemia (1); hypogonadism (1); inflammation (1).
A further 21 diseases each share a sentence with MC3R in 1 paper.